CR1 (complement C3b/C4b receptor 1 (Knops blood group))
Diseases named in the same sentence as CR1 in open-access papers (continued):
Sharing a sentence is not in itself a finding about the gene and the disease.
malaria (continued). "The results of the present study demonstrate that common CR1 variants significantly protect against severe malaria in an endemic area." (PMID 23152904, 2012). "Since the study revealed a significant association of CR1 polymorphisms (exon 22 and intron 27) with protection against severe malaria, possible role of these variants to the disease outcome was explored." (PMID 23152904, 2012). "Distribution of ‘B’ blood group and wild type of CR1 polymorphism (intron 27: AA/exon 22: AA) were significantly associated with severe malaria (OR = 14)." (PMID 23152904, 2012). "A process resembling transfer reaction of CR1 has been proposed to explain the loss of CD55 on RBC during malaria." (PMID 22206234, 2011). "Those SNP associations with severe malaria are well known and are commonly reported in the literature: CR1, IL4, TNF, G6PD, IL10." (PMID 20459687, 2010). "Low-CR1-expressing antigens impair rosette formation and thereby maybe reduce the risk of severe malaria." (PMID 41450567, 2025). "Reduced CR1 density on erythrocytes has been associated with an increased risk of severe malaria." (PMID 40993672, 2025). "Consequently, RBC CR1 deficiency caused by high expression of CR1-derived alleles is profoundly common in southern China malaria-endemic regions such as Guizhou and other SEAs." (PMID 38665582, 2024). "Polymorphisms associated with CR1 deficiency confer protection against severe Malaria." (PMID 38665582, 2024). "Therefore, the CR1 levels on erythrocytes and relevant polymorphisms have been associated with the response to P. falciparum Malaria in Malaria-endemic regions." (PMID 38665582, 2024). "The high CR1 expression in erythrocytes may contribute to a high clearance of immune complexes, and decrease inflammation caused by malaria." (PMID 36626386, 2023). "It has been suggested that the low-expression of CR1 is protective against severe malaria, thus higher frequency of the minor allele in Asia could be the result of selection pressure in malaria-endemic regions." (PMID 37591894, 2023). "CR1 polymorphisms could explain the association between altered efficiency of rosetting and malaria severity." (PMID 34408631, 2021). "Also, complementary receptor 1 (CR1) involved in the interaction between Plasmodium and cells, is taken as an index of malaria susceptibility or protection." (PMID 34277665, 2021). "Furthermore, as occurs with other genes encoding erythrocyte proteins, the CR1 polymorphism has been modified by natural selection for malaria resistance in populations of endemic regions." (PMID 30092084, 2018). "In the study, genetic and health information on more than 5,500 children in Kenya were analyzed to see if the severity of malaria differed depending on whether they had a CR1 mutation." (PMID 29690995, 2018). "The first were those polymorphisms involved in the pathogenesis of severe malaria such as CR1, which supports the hypothesis that damage from sequestration of malaria parasites in the microvasculature of the brain precipitates the seizures." (PMID 29750209, 2017). "RBC CR1 level in malaria-endemic African populations is a complex phenotype influenced by multiple factors that should be taken into account in the design and interpretation of future studies on CR1 and malaria susceptibility." (PMID 26844958, 2016). "RBC surface CR1 level can vary between individuals by more than 20-fold and may be associated with the risk of severe malaria." (PMID 26844958, 2016). "Moreover, lower levels of the complement receptor-1 (CR1) have been found in α-thalassemic red cells, and a reduction of infected red cells to form rosettes (associated to severe malaria) has been associated to CR1 deficiency." (PMID 24205432, 2013). "The observed relationship between CR1 polymorphisms and severe malaria remains inconsistent." (PMID 23152904, 2012).
malaria (continued). "Notably, four of the associated loci (ABO, HBB, DARC and CR1) have been implicated in resistance to malaria, a disease endemic in Sardinia until a few decades ago." (PMID 22291609, 2012). "CR1 deficiency and blood group O are thought to protect against malaria by decreased rosetting." (PMID 18173836, 2008). "Whatever the mechanism is by which CR1 is involved in the pathogenesis of malaria, knowledge of which alleles are associated with resistance or susceptibility to severe malaria will make it possible to observe the relationship between structure and function and susceptibility to severe malaria." (PMID 16277654, 2005). "In addition, mobilization of CR1 on the surface of Plasmodium-infected red blood cells is required for rosetting, a process implicated in vascular obstruction during severe malaria." (PMID 34408631, 2021). "However, erythrocyte CR1 deficiency may be detrimental in areas such as Thailand, where malaria transmission is low." (PMID 31455446, 2020). "CR1 has been identified as a key receptor for P.f invasion and plays multiple roles in the pathogenesis of malaria." (PMID 40993672, 2025). "In six analyses of different ethnic groups in Guizhou, the CR1 gene was screened simultaneously, verifying that CR1 plays a vital role in resistance to Malaria in Guizhou." (PMID 38665582, 2024). "Helgeson RBCs, which are a null variant of the Knops system, exhibited dramatically reduced rosetting, indicating that CR1-suppressed rosetting plays a role in malaria." (PMID 37104316, 2023). "Complement Receptor Type 1 (CR1) is a malaria-associated gene that encodes a transmembrane receptor of erythrocytes and is crucial for malaria parasite invasion." (PMID 36626386, 2023). "Our finding that rs11117991 determines CR1 expression allows for genotyping of the Helgeson phenotype and more precise investigation of its relation to malaria." (PMID 37591894, 2023). "This transcriptional upregulation of CR1 is in contrast to previous reports of down regulated CR1 on splenic monocytes/macrophages in murine models of malaria, and on CD16+ monocytes/macrophages in P. falciparum and P. vivax malaria patients from Peru47." (PMID 37968278, 2023). "We analyzed the signals of positive selection in the CR1 gene in diverse malaria-endemic populations using genome sequencing datasets." (PMID 36626386, 2023). "Our results clarify discrepancies reported in previous studies on the role of CR1 on the pathogenesis of malaria." (PMID 36626386, 2023). "Our results support the notion that BAFF-var is protective at least in part by inducing CR1, which increases the internalization of immunocomplexes by monocytes/macrophages, decreasing malaria severity." (PMID 33123155, 2020). "Human genetic studies provide additional support for the importance of CR1 in malaria host–parasite interactions." (PMID 31455446, 2020). "Global analysis of the BAFF-var allele on total RNA expression revealed many differentially expressed genes implicated in the immune response to malaria; among them, we selected CXCL10, CR1, MIF, ICAM-1, and NFKB2 for further analysis." (PMID 33123155, 2020). "Given the important biological role of CR1 in malaria host-parasite interactions, we aimed to clarify the relationship between the Sl and McC alleles and severe malaria in a case-control study of Kenyan children." (PMID 29690995, 2018). "In malaria, CR1 generates rosettes between Plasmodium falciparum infected and noninfected erythrocytes and mediates sialic acid–independent cell invasion." (PMID 30092084, 2018). "The higher expression of the TLR genes, GZMB, FOS, HSPA6, and CR1, in uncomplicated malaria cases during the late convalescence time point can be interpreted two ways." (PMID 26961973, 2016). "For example, the KEGG term “Malaria” is enriched in the UP genes in RA due to genes such as CR1, GYPA, ICAM1, PECAM1, and TLR4." (PMID 28491277, 2016).
malaria (continued). "An increasing body of evidence from in vitro studies supports a role for CR1 in the pathogenesis of severe malaria, yet little is known about the determinants of RBC CR1 level variation in African populations." (PMID 26844958, 2016). "The potential role of CR1 in the severity of malaria seems plausible since it has been shown that CR1 is involved in rosetting by binding to the P. falciparum erythrocyte membrane protein 1 (PfEMP1)." (PMID 24200236, 2013). "CR1 seems to play an important role in the pathogenesis of severe malaria by virtue of its capacity to rosette, form immune complexes (ICs) and facilitate entry of parasite into the RBCs." (PMID 23152904, 2012). "Association of CR1 polymorphisms, ABO blood group in treatment outcome patients with severe malaria." (PMID 23152904, 2012). "Despite these limitations in understanding of cause effect relationship, CR1 polymorphisms and ABO blood group system appear to affect the outcome of P.falciparum infection in malaria endemic areas." (PMID 23152904, 2012). "It is of interest then that haematin, a malaria parasite product, induces C3 degradation and deposition, and that its concentration correlates with surface expression of CR1 on B cells." (PMID 19121080, 2009). "The results obtained in the study presented here have biological significance and are further supportive evidence of the importance of CR1 in the pathogenesis of severe malaria." (PMID 16277654, 2005). "These investigators found that circulating E taken from children with malaria had low levels of CR1, and of decay accelerating factor (DAF), and C3 activation fragments could also be demonstrated on the E." (PMID 41230021, 2025). "Our hypothesis is that the covalent deposition of C3 activation fragments on or close to CCP CR1 and DAF on E constitutes the most important mechanism for loss of np‐E in malaria." (PMID 41230021, 2025). "Interestingly, the CR1 gene was screened simultaneously, suggesting that CR1 plays a vital role in resistance to Malaria in Guizhou." (PMID 38665582, 2024). "While CR1 is known to have an important role in malaria the variants affecting these four candidate motifs do not appear to have undergone evolutionary selection in malaria-affected populations." (PMID 37591894, 2023). "Moreover, CR1 has been suggested to be one of the top targets that is heavily influenced by malaria pressure." (PMID 37591894, 2023). "A protective effect of low CR1 expression against malaria has been suggested." (PMID 36626386, 2023). "In addition, CR1 is a well-known host receptor hijacked by malaria parasites (Plasmodium falciparum) to invade red blood cells (RBCs) during the blood stage of the malaria life cycle." (PMID 36626386, 2023). "In addition, we observed that malaria-driven selection had occurred in the HNL, with population-specific variants of malaria-related genes (e.g., CR1) present." (PMID 36173765, 2022). "In malaria, CR1 plays a role in both rosetting and parasite invasion of erythrocytes." (PMID 31455446, 2020). "Other protective red blood cell (RBC) polymorphisms have also been shown to occur at their highest frequencies in malaria endemic populations, including glucose-6-phosphatase (G6PD) deficiency, the O blood group, and variants of the gene for complement receptor 1 (CR1)." (PMID 32130487, 2020). "For example, iRBCs inhibit monocyte surface expression of complement receptor 1 (CR1 or CD35), and thus impair phagocytosis of circulating immune complexes that can bind to active C3b and C4b, potentially contributing to inflammatory pathology in malaria." (PMID 30581439, 2018). "CR1 has been shown to be protective against P. falciparum infections in low concentrations, but when over-expressed it can lead to rosetting of blood cells and subsequent severe malaria." (PMID 26961973, 2016). "Another uncertainty is whether the variation in RBC CR1 level that we describe here has functional significance in terms of malaria host–parasite interactions." (PMID 26844958, 2016).
malaria (continued). "Malaria endemicity affects the erythrocyte CR1 expressions and its function." (PMID 23152904, 2012). "Correlation between CR1 polymorphisms (Sl2/Sl2 vs. Sl1/Sl1) and resistance to severe malaria was reported in a western Kenyan population, but not in two studies of populations from The Gambia." (PMID 22506052, 2012). "The homozygous polymorphisms of CR1 intron 27 and exon 22 (TT and GG) and alleles (T and G) that are associated with low expression of CR1 on red blood cells, conferred significant protection against CM, MOD and malaria deaths." (PMID 23152904, 2012). "High frequencies of host erythrocyte polymorphisms such as α+-thalassaemia, haemoglobin (Hb) S, Hb C, Hb E, complement receptor-1 (CR1) deficiency, glucose-6-phosphate dehydrogenase (G6PD) deficiency and south-east Asian ovalocytosis (SAO) are found in malaria endemic areas." (PMID 18173836, 2008). "The study of the Sl and McC blood group antigens may offer further clues as to the role of CR1 in the pathogenesis of severe malaria." (PMID 16277654, 2005). "Evidence from several studies suggests that the complement receptor 1 (CR1, CD35) may be involved in the pathogenesis of severe malaria." (PMID 16277654, 2005). "Moreover, the complement factor 1 (CR1) gene, suggested to be involved in malaria susceptibility, and the FCGR2B gene, demonstrated to harbor malaria protective alleles, were also identified by our analysis, thus strengthening the mark of malaria in the Italian genome." (PMID 26553317, 2015). "Conversely, malaria may not be the driving force behind the selective pressure of CR1 polymorphisms." (PMID 24200236, 2013). "This study would support the hypothesis that ABO blood group and CR1 deficiency associated with the L allele protect against malaria by reduced rosetting and associated pathology rather than parasite density." (PMID 18173836, 2008). "The mechanism by which the Sl2 and McCb alleles could confer protection from severe malaria is not known, since these polymorphisms are located near the C-terminus of the CR1 molecule in an area that is outside the binding sites for C3b, C4b, and PfEMP-1." (PMID 16277654, 2005). "As proof-of-concept, we aimed to delineate the low-expressing complement receptor 1 (CR1) Helgeson phenotype on erythrocytes, which is correlated with several diseases and protects against severe malaria." (PMID 37591894, 2023). "The reduced expression of CR1 and CD55 on RBCs in severe anemia from both P. falciparum or P. vivax supports the hypothesis that RBCs with lower expression of CRPs are associated with RBC destruction and that this is a species-transcending mechanism of malaria anemia." (PMID 30429373, 2018). "The leishmaniasis pathway had three probes in common with malaria (TLR2, TLR4, CR1), while Staphylococcus aureus infection had one (CR1)." (PMID 26961973, 2016). "Differentially expressed probes form these canonical pathways that were previously shown to play a role in severe malaria pathogenesis were TLR2, TLR4, TLR8, HSPA6, CR1, C1qA, C1qB, C1qC, FOS, and GZMB." (PMID 26961973, 2016). "In addition, they are exposed to different groups of infectious agents compared to their African counterparts, which in turn directs immune system development, as shown in complement receptor-1 (CR1) polymorphisms in malaria-endemic and non-endemic populations." (PMID 25755928, 2015). "In the unadjusted analysis, CR1 and CD55 were more influential than malaria status, parasite density, or IC binding capacity both in the global and in the subgroup analyses." (PMID 18717995, 2008). "After adjustment for all the confounding effects, malaria status and CD55 made the most significant contribution after age when all the samples were included, while CR1 showed a trend towards significance (P = 0.07)." (PMID 18717995, 2008).
malaria (continued). "In addition to being present on RBCs, CR1 is also present on follicular dendritic cells, macrophages and T and B lymphocytes and, therefore, may also have immunoregulatory functions that affect the development of immunity against malaria." (PMID 16277654, 2005). "We assessed selection signals on the CR1 gene locus in nine malaria-endemic and two non-endemic population groups." (PMID 36626386, 2023). "COMPLEMENT RECEPTOR 1 (CR1), a membrane immune adherence receptor that plays a critical role in the capture and clearance of complement-opsonized pathogens, was upregulated on both CD14+ and CD16+ monocytes and cDCs during malaria." (PMID 37968278, 2023). "Uninfected RBCs from patients with severe malaria anemia had lower surface expression of CR1 than those from patients with nonanemic infection." (PMID 30429373, 2018). "Three other loci (CR1, TNF, and TLR4) showed borderline associations with the principal component 2 but not with any particular measure of malaria transmission." (PMID 28541483, 2017). "Two previous studies have shown that RBC CR1 expression level varies with age in both malaria-endemic and non-endemic populations, being lowest during early childhood." (PMID 26844958, 2016). "In Plasmodium falciparum infection, complement receptor-1 (CR1) on erythrocyte’s surface and ABO blood group play important roles in formation of rosettes which are presumed to be contributory in the pathogenesis of severe malaria." (PMID 23152904, 2012). "Although overall unadjusted changes in CR1, CD55, and IC binding capacity across age groups were statistically significant, only a limited number of comparisons were statistically significant after adjustment for malaria status and parasite density." (PMID 18717995, 2008). "Another consideration is that although all children positive for malaria on a thick film were excluded, information on other infective or inflammatory conditions that might influence CR1 copy number was not available." (PMID 29259218, 2017).